RGS4 (regulator of G protein signaling 4)
Diseases named in the same sentence as RGS4 in open-access papers (continued):
Sharing a sentence is not in itself a finding about the gene and the disease.
tumor (25 papers, 2007 to 2026). "Further analysis found that RGS4 expression was closely associated with tumor stage, increased from stage I to other stages." (PMID 38693916, 2024). "Functional experiments demonstrated that Rgs4 enhances tumor cell proliferation and inhibits apoptosis." (PMID 42099385, 2026). "We then constructed ATC cell lines with stable overexpression of RGS4 to explore the effects of RSG4 on the anti‐tumour activities of OPD'." (PMID 39153211, 2024). "Here, for the first time, we studied the correlation between RGS4 and fibroblasts, and found that RGS4 was significantly positively correlated with fibroblast infiltration in the tumor immune microenvironment." (PMID 38693916, 2024). "Especially, the scRNA-seq study revealed a considerable upregulation of RGS4 in the fibroblast population, hence playing a crucial role in tumour invasion and the modulation of the extra-tumoral stroma." (PMID 38978046, 2024). "Given that the potential significant functions of RGS4 in the anti‐tumour activities of OPD', we first verified the effect of OPD' on RGS4 expression." (PMID 39153211, 2024). "Our study found that RGS4 is closely related to signaling pathways related to tumor formation and metastasis." (PMID 38693916, 2024). "In a nude mouse metastasis model, overexpression of RGS4 was shown to inhibit the metastatic process of tumours in vivo." (PMID 37924113, 2023). "Inhibited tumor migration and invasion by inhibiting proteasomal activity and increasing the levels of RGS4.Inhibited tumor growth and invasion." (PMID 34026649, 2021). "They showed that RGS4 knockdown inhibits cell proliferation and induces apoptosis, and that RGS4 negatively regulates the tumor suppressor, microRNA-16." (PMID 34748583, 2021). "In summary, in the prognostic signature, some genes (MUC1, RGS4) have been reported to promote tumor cell growth." (PMID 33889544, 2021). "Here, we found that RGS4 silencing decreased the expression, secretion and activity of MMP2, a key MMP associated with tumor dissemination and invasiveness." (PMID 32392739, 2020). "On the other hand, functioning as a tumor suppressor, RGS4 inhibited tumor metastasis and invasiveness by regulating EMT-related markers and MMPs." (PMID 29108247, 2017). "For example, high expression of RGS4, which was downregulated in our SIN3A knockdown gene list, has been associated with inhibition of migration, invasion and delayed tumor growth of MDA-MB-231 cells." (PMID 27780928, 2016). "Our results suggest that high expression of RGS4 is closely related to fibroblast infiltration and stroma formation in the tumor immune microenvironment, which may promote tumor development and metastasis." (PMID 38693916, 2024). "Additionally, ADA is linked to RGS4 and LYN, highlighting its role in purine metabolism and immune response modulation in the tumor microenvironment." (PMID 39267843, 2024). "Our results suggest that RGS4 plays a partial role in suppressing tumor progression." (PMID 34748583, 2021). "However, the increased RGS4 expression enhanced by IGF2BP1 depresses tumor cell migration and invasion." (PMID 29954406, 2018). "For example, IGF2BP1 expression might upregulate RGS4 mRNA and inhibit tumor cell proliferation and invasion, while downregulate GDF15, IGF2, and PTG2 mRNAs and lead to suppression of tumor cell proliferation and invasion." (PMID 29954406, 2018). "RGS4 can form complex signalling molecule transduction complexes with different receptors, effectors, scaffolding proteins and other signalling molecules, affecting the localization, activity and stability of signals in cells and playing an important regulatory role in tumour tissues or cells." (PMID 37924113, 2023).
tumor (continued). "Taken together, our study robustly substantiated the promising anti‐tumour activity of OPD' in ATC and elucidated the mechanism that OPD' bind with JUN to repress RGS4 transcription, consequently inducing cell cycle arrest and apoptosis in ATC cells." (PMID 39153211, 2024). "Furthermore, the tumor suppressing function of miR-107 has been previously reported in HCC via targeting oncogenic genes, including RGS4, HMGA2, HMGCS2, cofilin-1, and Wnt/β-catenin." (PMID 37744274, 2023). "Moreover, the results of q-RT PCR showed that CTSV, RGS4, SYT13 and NPTX1 were highly expressed in tumor tissues compared with adjacent tumor tissues, while SLC25A15, ENTPD2 and CA8 were low expressed." (PMID 36684237, 2022). "Since RGS4 was up-regulated and PTGS2 was down-regulated in IMP1-expressing cells and xenografts, the data indicated that the function of IMP1 in suppressing tumor cell proliferation and invasion could through the regulation of its bound mRNAs." (PMID 26910917, 2016). "However, further study needs to be carried out to determine the level of RGS4 and RGS5 expression in other types of cancer and explore whether RAD6A/B can regulate the RGS proteins in cancer cells to induce tumor progression." (PMID 34199813, 2021).
cancer (20 papers, 2007 to 2023). A tumor composed of atypical neoplastic, often pleomorphic cells that invade other tissues. "Regulators of G-protein signaling 4 (RGS4) are negative regulators of G-protein signaling, and elevated levels of RGS4 are reportedly linked with several human diseases, including cancer." (PMID 32392739, 2020). "Previous studies reported that RGS4 gene expression were associated with invasion of several cancer." (PMID 21698121, 2011). "RGS4, a GTPase-activating protein, changes in its expression levels can affect apoptosis, invasion and migration capacity and is linked to the development of diseases such as cancer." (PMID 36309699, 2022). "Regulators of G protein signaling 4 (RGS4) are negative regulators of G protein signaling, and elevated RGS4 levels have been reported to be associated with a variety of human diseases, including cancer (Xue, Wang, Meng, Jiao, & Dang, 2017)." (PMID 35646090, 2022). "Trans-well assays were performed to investigate RGS4 effect on the migration and invasion of cancer cells in vitro." (PMID 29108247, 2017). "Meanwhile, the involvement of RGS4 in cancer has also got growing studies." (PMID 29108247, 2017). "Our results suggest that PAR4 activation contributes to cancer progression, which is attenuated in the presence of RGS2, RGS4, and RGS16." (PMID 32517689, 2020). "Previous studies reported that several RGS proteins, including RGS2, RGS4, and RGS5, were involved in cancer development." (PMID 28724429, 2017). "Numerous studies have proved that FABP4, COL4A1, and RGS4 were related to various types of cancer progression; however, we searched GIST on PubMed with no reports on our screened differential genes and GIST." (PMID 35646090, 2022). "RGS4′s implication in cancer is not well documented, other than as a novel regulator in malignant melanoma." (PMID 32392739, 2020). "Furthermore, PAR4 activation promoted cell proliferation and cancer-related gene expression, which were attenuated by RGS2, RGS4, and RGS16." (PMID 32517689, 2020). "Finally, PAR4-mediated HT29 cancer cell progression was significantly inhibited by RGS2, RGS4 and RGS16, as determined based on PAR4-activated cell proliferation and expression patterns of cancer progression-related genes." (PMID 32517689, 2020). "Targeting RGS4 likewise diminished the expression of decorin, an extracellular matrix (ECM) protein engaged in the cell growth, differentiation, proliferation, adhesion and metastasis of various cancers." (PMID 32392739, 2020). "Additionally, both RGS2 and RGS4 attenuated PAR4-activated downstream signaling and cancer progression." (PMID 32517689, 2020). "Misexpression of RGS2, RGS4, and RGS5 has also been reported in a number of these cancers." (PMID 23637832, 2013).
infection (4 papers, 2018 to 2024). The state of being infected such as from the introduction of a foreign agent such as serum, vaccine, antigenic substance or organism. "Infection with both the scrambled-shRNA lentivirus and the RGS4-shRNA lentivirus resulted in a substantial long-red fluorescent signal in more than 90% of the astrocytes." (PMID 38391904, 2024). "The evaluation of mCherry-associated fluorescence revealed a high infection efficiency with the detection of more than 90% of positive cells, both for the control and RGS4-encoding viruses, while no fluorescence signal was observed in non-infected cells." (PMID 38391904, 2024). "When specifically examining the cells responding with a peak–plateau profile, we determined that the slope of the Ca2+ concentration decay (plateau-phase) was significantly higher after RGS4 infection, indicating a faster decrease in the cytosolic Ca2+ concentration during the exposure to DHPG." (PMID 38391904, 2024). "ARG2 (p = 0.040, <0.001, and <0.001, respectively) and RGS4 (p = 0.044, = 0.021, and = 0.023, respectively) expression levels after 30, 100, and 300 MOI AdNKX2-1 infection was significantly higher than those after AdLacZ infection." (PMID 34748583, 2021). "We investigated ARG2, RGS4, and RGS5 protein expression by western blot analysis of whole cell lysates extracted from BHP18-21v cells 72 h after 300 MOI AdLacZ or AdNKX2-1 infection." (PMID 34748583, 2021). "Of note, three of the four genes that were significantly regulated in all investigated conditions showed lessened induction upon concomitant infection and Smh1 expression (IL-1β, GLIS3, and MIR3142HG), while down-regulation of the fourth factor (RGS4) is accentuated by Smh1 expression." (PMID 36411449, 2022). "For further investigation, we selected three genes, ARG2, RGS4, and RGS5 based on the following criteria: there was an apparent expression 6 h after infection, the ratio 12 h after infection was more than twice, and the ratio 24 h after infection was >10-fold." (PMID 34748583, 2021). "ARG2, RGS4, or RGS5 expressions were not induced 72 h after 30, 100, 300, and 1000 MOI AdNKX2-1 infection in HepG2 cells." (PMID 34748583, 2021).
neurological disorders (4 papers, 2009 to 2024). "In the striatum, RGS4 is highly expressed, regulates Gq and Gi/o, and has been implicated in the regulation of cholinergic and dopaminergic signaling, being relevant in several neurological disorders, including PD." (PMID 39565858, 2024). "Indirect signaling modulators such as RGS4 inhibitors, used in combination with receptor ligands, could pave the way for new therapeutic approaches for diverse neurological disorders with improved efficacy and selectivity." (PMID 38391904, 2024).
psychiatric disorder (4 papers, 2012 to 2025). A disorder characterized by behavioral and/or psychological abnormalities, often accompanied by physical symptoms. "Rgs4 is implicated in intestinal inflammation, cardiovascular diseases and psychiatric disorders." (PMID 22545125, 2012). "RGS4 plays an important role in regulating smooth muscle contraction, cardiomyocyte development, neural plasticity and psychiatric disorders." (PMID 22545125, 2012). "Hsa-miR-874-3p, associated with many psychiatric disorders, might target the +789–+1152 region in the 3′UTR of the RGS4 gene." (PMID 39202417, 2024). "Regulator of G-protein Signaling 4 (RGS4) plays an important role in regulating smooth muscle contraction, cardiac development, neural plasticity and psychiatric disorder." (PMID 22545125, 2012).
heart disease (3 papers, 2021 to 2022). "It suggests that RGS4 may be involved in the occurrence and development of cardiac diseases, so this study will explore the regulatory process of RGS4 in cardiac fibrosis." (PMID 33892733, 2021).
RGS4 also shares sentences with these, for which no sentence is quoted: cardiovascular disease (2 papers); colorectal cancer (2); essential hypertension (2); hepatocellular carcinoma (2); Hypertension (2); Parkinson (2); anaplastic thyroid cancer (1); Anxiety (1); autism (1); Bradycardia (1); cardiomyopathy (1); dementia with Lewy bodies (1); diabetic kidney disease (1); epilepsy (1); Glucose intolerance (1); Hearing Loss (1); Hepatic steatosis (1); hypertrophy (1); hypothyroidism (1); influenza (1); Insulin resistance (1); invasive breast carcinoma (1); ischemic cardiomyopathy (1); leiomyoma (1); lung adenocarcinoma (1); melanocytic nevus (1); mental disorder (1); metabolic disorders (1); Nephroblastoma (1); neural tube defect (1).
A further 8 diseases each share a sentence with RGS4 in 1 paper.